COL1A1 (collagen type I alpha 1 chain)
Diseases named in the same sentence as COL1A1 in open-access papers (continued):
Sharing a sentence is not in itself a finding about the gene and the disease.
chronic pancreatitis (4 papers, 2015 to 2023). A chronic inflammatory process causing damage and fibrosis of the pancreatic parenchyma. "Our STP mice exhibited advanced ADM, increased fibrosis, increased numbers of PanIN lesions, overexpression of chronic pancreatitis-related marker Muc6, and elevated expression of desmoplasia-associated marker Col1A1, compared to the MT-TGFα mice." (PMID 25803032, 2015). "Therefore, we further assessed the expression of molecular markers that are associated with chronic pancreatitis (Muc6) or desmoplastic reaction (Ctgf1 and Col1A1)." (PMID 25803032, 2015). "In PDAC, COL1A1 can also be used as a biomarker to provide histologic presentations of human chronic pancreatitis transitioning to early tumorigenesis." (PMID 31428151, 2019). "In addition, we assessed the activation of PSCs by determining the levels of Col1a1, Mmp9, and Il6 factors previously shown to be upregulated in PSCs during chronic pancreatitis." (PMID 36835366, 2023).
cutaneous melanoma (4 papers, 2021 to 2022). A primary melanoma arising from atypical melanocytes in the skin. "In skin cutaneous melanoma (SKCM), COL1A1 mutations were the most prevalent (71%)." (PMID 36032075, 2022).
deafness (4 papers, 2012 to 2023). An inherited or acquired condition characterized by the complete loss of the ability to hear from one or both ears. "We identified five predicted highly suspected deafness-associated genes, namely, COL1A1, GJC3, RRM2B, SALL4 and SALL1, in the available databases, including Ensemble and OMIM, indicating that they were correctly identified as deafness-associated genes." (PMID 36803022, 2023). "The deafness gene panel also detected other gene variants (i.e COL1A1, ITM2B), but their pathogenicity was uncertain as per the American College of Medical Genetics guidelines." (PMID 36064591, 2022).
diabetic cardiomyopathy (4 papers, 2021 to 2025). Diabetic cardiomyopathy is a disorder of the heart muscle in people with diabetes. "Moreover, cardiac fibrosis was also alleviated by QLQX treatment in mice with STZ-induced diabetic cardiomyopathy as evidenced by Masson staining and the expression levels of Col1a1 and Col3a1." (PMID 34336956, 2021). "The salient findings from the present study support that Cyp1a1, a significantly upregulated DEG, has the highest connectivity in the PPI interaction network among the top five hub genes (Cyp1a1, Cyp2e1, Col1a1, Col3a1, Col1a2) to affect the cardiac function in STZ-induced diabetic cardiomyopathy." (PMID 35387435, 2022).
disc degeneration (4 papers, 2016 to 2025). "OI patients with COL1A1/COL1A2 mutations may have heightened susceptibility to disc herniation despite modest disc degeneration." (PMID 40760627, 2025). "COL1A1 Sp1 genotype increased the risk of disc degeneration in elderly Dutch patients." (PMID 34178503, 2021). "Our analysis showed that COL1A1 Sp1 polymorphism was also associated with susceptibility to IVDD and TT genotype conferred more than threefold risk to disc degeneration than GG genotype." (PMID 34663366, 2021). "Previous studies identified a correlation of a Sp1-binding site polymorphism of COL1A1 (+ 1245G > T, rs1800012) with IVDD risk that carriers of TT genotype were more vulnerable to disc degeneration." (PMID 34663366, 2021). "Histological examinations and aggrecan, Col1A1, Col2A1 and matrix metalloprotease (MMP)-3 mRNA expression confirmed the disc degeneration, supporting the imaging results." (PMID 26924131, 2016).
Duchenne muscular dystrophy (4 papers, 2020 to 2025). Duchenne muscular dystrophy (DMD) is a neuromuscular disease characterized by rapidly progressive muscle weakness and wasting due to degeneration of skeletal, smooth and cardiac muscle. "In Duchenne muscular dystrophy, the expression of the COL1A1 gene can be reduced by a tyrosine kinase inhibitor, nintedanib, and this reduces the degree of SMF." (PMID 39091264, 2024). "HT-100, a COL1A1 inhibitor, was developed for the treatment of Duchenne muscular dystrophy (DMD) by the Akashi Therapeutics pipeline and Collgard Biopharmaceuticals." (PMID 38195542, 2024).
dyslipidemia (4 papers, 2019 to 2025). "In this study, we mainly focused on the relationship of the SNPs in the COL1A1 3′-UTR to dyslipidemia risk and outcome." (PMID 30642348, 2019). "Therefore, in obese, when the COL1A1 expression changed, it may lead to serum TG increased and cause dyslipidemia." (PMID 30642348, 2019). "We hypothesized that COL1A1 as the hub gene was closely relevant to dyslipidemia occurs." (PMID 30642348, 2019).
gastric tumor (4 papers, 2021 to 2024). "The hazard ratio of CAF infiltration in COL1A1, COL5A1, ITGA4, EMILIN1, and TSPAN9 signature was even higher, presenting a 36.8 times higher risk of death in gastric tumors with high CAF infiltration." (PMID 35739492, 2022). "Elevated expression of COL1A1 was observed in gastric tumor tissues in high stage (stage II, III and IV) compared with normal tissues or tumor tissues in stage I." (PMID 34319913, 2021). "Among the signature genes we identified in this study, targeting the COL1A1, COL5A1 and ITGA4 may have a therapeutic potential in gastric tumors with high CAF infiltration." (PMID 35739492, 2022).
glomerulosclerosis (4 papers, 2017 to 2021). A hardening of the kidney glomerulus caused by scarring of the blood vessels. "As molecular drivers of glomerulosclerosis in diabetic UNx and UNx-Renin mice, our glomerular gene expression analysis confirmed the upregulation of several fibrogenesis-associated genes (e.g. Col1a1, Col5a1, Col5a3, Fn1 and Mmp14)." (PMID 34494644, 2021). "Furthermore, SFN treatment (5/6NX + HA + SFN group) significantly reduced the fibrosis area, glomerular sclerosis index, and fibrotic protein levels (COL1A1, VIM, and ACTA2) compared with those in the 5/6NX + HA group." (PMID 32854194, 2020). "Consistent with marked glomerulosclerosis in UNx-Renin mice, ECM-associated gene expression changes were more pronounced in UNx-Renin mice, in which additional markers of fibrogenesis were significantly upregulated, including Col1a1, Col3a1, Col6a1, Col6a2 and Mmp7." (PMID 34494644, 2021).
hepatic (4 papers, 2017 to 2025). "Differential regulation of the hepatic stellate cell activation and hepatic fibrosis pathways was largely driven by upregulation of 17 collagen isoforms, including COL12A1, COL15A1, COL16A1, and COL1A1." (PMID 40040391, 2025).
hypophosphatasia (4 papers, 2019 to 2025). Hypophosphatasia (HPP) is a rare heritable metabolic disorder characterized by defective mineralization of bone and/or teeth in the presence of reduced activity of unfractionated serum alkaline phosphatase (ALP). "Genetic analysis is, however, recommended in those rare cases where clinical and laboratory tests suggest a monogenic bone disease (e.g., hypophosphatasia, Gaucher disease, and juvenile osteoporosis due to COL1A1 mutations)." (PMID 29948835, 2019).
intracranial aneurysms (4 papers, 2013 to 2022). "COL1A1 and COL1A2 were shown to be direct targets of miR-513b-5p in patients with intracranial aneurysms." (PMID 36327243, 2022). "Collagen-type I alpha 1 chain (COL1A1) and COL1A2 are abnormally expressed in intracranial aneurysm (IA), but their mechanism of action remains unclear." (PMID 34290266, 2021).
ischemic stroke (4 papers, 2022 to 2024). A stroke disorder caused by obstruction of blood flow to the brain, due to thrombotic (local blood clot formation) or embolic (due to a blood clot or other material traveling from another site) event. "As shown in scRNA-seq analysis, ischemic stroke injury induced higher numbers of Iba1+ microglia derived from NG2-tdT+ than physical injury did, and physical injury triggered higher numbers of Col1a1+ fibroblasts from NG2-tdT+ than ischemic stroke injury did." (PMID 39431007, 2024). "Many of the identified genes, including TLR2, TLR3, TLR9, GRN, COL1A1, FN1, and LAMB1, were reported as upregulated genes in previous reports of ischemic stroke." (PMID 35887140, 2022).
mastitis (4 papers, 2014 to 2022). Inflammation of breast tissue during lactation or postpartum due to an obstructed duct or infection. "Therefore, regulating the bovine COL1A1 expression for reducing tissue damage may be a cost-effective way to reduce the losses caused by mastitis." (PMID 25273983, 2014). "The upregulated expression of collagen type I alpha 1 (COL1A1) and inter-alpha (globulin) inhibitor H4 (ITIH4) in mastitis may be associated with host tissue damage and repair during the late stages of infection." (PMID 36142648, 2022). "The differentially expressed proteins we discovered in this study, such as COL1A1 and ITIH4, may serve as potential genes for the susceptibility to mastitis in dairy cows." (PMID 25273983, 2014). "Up-regulation of collagen, type I, alpha 1 (COL1A1) and inter-alpha (Globulin) inhibitor H4 (ITIH4) in the mastitis-infected tissue was confirmed by Western blotting and Immunohistochemistry." (PMID 25273983, 2014). "Firstly, the relative expressions of COL1A1 (~50 kDa) and ITIH4 (~100 kDa) in the healthy and mastitis-infected cows’ mammary gland tissues were investigated by the Western blotting." (PMID 25273983, 2014).
nasopharyngeal carcinoma (4 papers, 2021 to 2024). A carcinoma arising from the nasopharyngeal epithelium. "The expression of COL1A1 exerted a radio-resistance effect in nasopharyngeal carcinoma cells." (PMID 35274048, 2022). "Another study showed that hsa-miR-29-3p was expressed at low levels in nasopharyngeal carcinoma and could target COL1A1 to improve the radiosensitivity of nasopharyngeal carcinoma cells." (PMID 35201491, 2021). "Our present study showed that COL1A1 and COL3A1 were targeted by hsa-miR-29a/b/c that were decreased in radio-resistant nasopharyngeal carcinoma cells." (PMID 35274048, 2022).
neuroblastoma (4 papers, 2018 to 2024). Neuroblastoma (NB) is the most common solid, extracranial childhood tumor. "We also hypothesize that the association with the previous history of neuroblastoma could be influenced by the presence of COL1A1 mutation, whose role has been already described in the behavior and progression of some cancers." (PMID 35456387, 2022). "We obtained this PDX tissue and used immunohistochemistry to stain for COL1A1 protein, a classical neuroblastoma mesenchymal marker." (PMID 38898465, 2024). "We analyzed the expression of endothelial markers (EGFL7, FLT1, PTPRB33), mesenchymal cells (COL1A2, COL1A1, PDGFRB34,35) and immune markers (ITGAM, CD247, PTPRC36–38) in MYCN-amplified neuroblastoma patient samples (with at least 90% tumor purity) and tumors from Protocol #4." (PMID 39367051, 2024).
non-alcoholic steatohepatitis (4 papers, 2020 to 2022). "ADMSCs ameliorate the development of fibrosis during the progression of nonalcoholic steatohepatitis Col4a1 and Col1a1 were significantly downregulated." (PMID 34985174, 2022). "Pioglitazone decreases hepatic TGF‐β1 and COL1A1 in non‐alcoholic steatohepatitis of mice." (PMID 33058500, 2020).
osteonecrosis (4 papers, 2017 to 2024). A none disease characterized by death of bone tissue due to a lack of blood supply. "Only gene polymorphism in the Sp1-binding site of Col1A1 showed a significant association in patients with osteonecrosis (p=0.045)." (PMID 30251958, 2019). "Only the Col1A1 Sp1-binding site gene polymorphism showed a significant association in ALL patients with osteonecrosis." (PMID 30251958, 2019). "The association between Col1A1 Sp1-binding site gene polymorphisms and osteonecrosis has to be assessed in a larger group of ALL survivors." (PMID 30251958, 2019). "In our study, only gene polymorphism in the Sp1-binding site of Col1A1 showed a significant association in ALL patients with osteonecrosis, but not for other bone abnormalities." (PMID 30251958, 2019). "Disruption of osteoblastic differentiation can lead to osteonecrosis, demonstrated by the downregulation of osteoblast-specific markers such as RUNX2 and COL1A1 in the osteonecrosis of femoral head." (PMID 39407304, 2024). "By targeting SMAD7, miR-17-5p promotes nuclear translocation of β-catenin, enhances expression of COL1A1 (Collagen Type I Alpha 1 Chain) and finally facilitates the proliferation and differentiation of femoral head mesenchymal stem (HMS) cells promoting osteonecrosis." (PMID 29050357, 2017). "Furthermore, the stimulatory effect of miR-17-5p over the expression of COL1A1 was also described in patients with non-traumatic osteonecrosis, as a consequence of the inhibition of SMAD7." (PMID 37239902, 2023).
otosclerosis (4 papers, 2013 to 2023). Formation of spongy bone in the labyrinth capsule which can progress toward the stapes (stapedial fixation) or anteriorly toward the cochlea leading to conductive, sensorineural, or mixed hearing loss. "Here, we genotyped eight previously associated variants in the following six candidate genes: RELN, BMP2, FGF2, COL1A1, TGFB1, and PPP2R5B in a large UK case–control otosclerosis cohort (n = 748)." (PMID 29728750, 2018). "It has been reported that COL1A1, BMP2, BMP4, TGFB1, and RELN genes may also contribute to the development of otosclerosis." (PMID 23864959, 2013).
periodontitis (4 papers, 2021 to 2026). An acute or chronic inflammatory process that affects the tissues that surround and support the teeth. "Cheng and Shen34 also identified COL1A1 as a key gene implicated in the pathophysiology of periodontitis, highlighting its critical role in maintaining periodontal tissue homeostasis." (PMID 41502450, 2026). "There is moderate evidence that P. intermedia is a pathogen associated with periodontitis, but we found that its pathogenic component, LPS, promoted osteogenesis and upregulated expression of COL1A1, OCN and RUNX2 in vitro." (PMID 36530443, 2022). "Administration showed that moderate ER stress could inhibit alveolar bone loss in periodontitis by upregulating expression of RUNX2, COL1A1 and OCN." (PMID 36530443, 2022). "Immunohistochemical staining demonstrated that the periodontitis group showed increased expression of the inflammatory marker (TNFα), along with decreased levels of AFF4 and osteogenic protein (RUNX2, COL1A1)." (PMID 37731335, 2024). "In addition, the enhanced Col1a1 expression observed in cells incubated with Synergoss Red could be of particular importance in treating periodontal disease, given that expression of type I collagen mRNA is shown to be reduced in the proximity of periodontal pockets of patients with periodontitis." (PMID 34063147, 2021).
pulmonary hypertension (4 papers, 2020 to 2023). Increased pressure within the pulmonary circulation due to lung or heart disorder. "A few reports have shown that COL1A1 is a major cause of pulmonary artery stiffening and decreased right ventricular systolic function in hypoxia pulmonary hypertension." (PMID 34310344, 2021). "CIRP-/- mice showed attenuated induction of α-SMA and collagens (Col1a1, Col3a1), reduced hydroxyproline content, decreased histological fibrosis scores, and improved pulmonary hypertension as compared to WT mice." (PMID 35377906, 2022).
systemic sclerosis (4 papers, 2023 to 2025). A chronic disorder, possibly autoimmune, marked by excessive production of collagen which results in hardening and thickening of body tissues. "Besides Smads, AP2 has also been found to bind the COL1A1 promotor in TGFβ-challenged dermal fibroblasts from systemic sclerosis patients." (PMID 37373151, 2023). "Notably, in systemic sclerosis (SSc), TGF-β drives fibroblast transition via Smad signaling, whereas baricitinib’s EGFR affinity downregulates COL1A1/COL3A1 to restore collagen density in skin models." (PMID 41585231, 2025).
type 2 diabetes (4 papers, 2021 to 2025). "Our study also identifies a novel association between the COL1A1 rs1107946 AA genotype and an increased risk of type 2 diabetes." (PMID 40507792, 2025). "Thus, COL1A1 is a novel potential therapeutic target for alleviating type 2 diabetes." (PMID 35281591, 2022).
Ureteral obstruction (4 papers, 2018 to 2025). Obstruction of the flow of urine through the ureter. "We measured transcript levels of Col1a1 and Col3a1 in the WT and Il17ra−/− kidneys following ureteral obstruction." (PMID 30405320, 2018). "Moreover, unilateral ureteral obstruction (UUO)-induced CKD models increased levels of TGF-β and the renal fibrotic genes Col1a1 and Fibronectin-1." (PMID 40141345, 2025).
Arrhythmia (3 papers, 2018 to 2022). Any cardiac rhythm other than the normal sinus rhythm. "Respondents were asked about seven other conditions or genetic variants, five of which were associated with health risks (connective tissue disorders, HCM, LQTS, cardiac arrhythmias, and COL1A1 variants) and two of which were associated with performance (ACE II and ACTN 3 variants)." (PMID 30424536, 2018). "In addition, telemetry echocardiography analysis suggested that arrhythmias were likely to occur in Zip13-KO mice, in which elevated levels of the cardiac fibrosis marker Col1a1, vascular inflammation-related gene eNOS, and Golgi-related molecule GM130 were observed." (PMID 36269775, 2022).
brain tumors (3 papers, 2016 to 2025). "Further validation of 110 potential noninvasive biomarkers yields three biomarker panels comprising a total of 19 biomarkers (including DES, VWF, and COL1A1) for accurate discrimination of two types of brain tumors and normal controls." (PMID 39716938, 2025). "Most members of collagens are closely associated with the genesis and the development of several malignancies, so COL1A1 behaves high expression in prostate, esophageal, brain tumor, pancreatic many malignant tumors." (PMID 27626164, 2016).
cardiac interstitial fibrosis (3 papers, 2022 to 2024). "In line with cardiac interstitial fibrosis, the LV mRNA expression levels of the collagens I (Col1a1) and III (Col3a1) were increased in mice with TAC (as compared with sham)." (PMID 37227779, 2023).
collagenopathies (3 papers, 2020 to 2021). "The autosomal dominant form of infantile cortical hyperostosis in humans (OMIM 114000) is described as a collagenopathy caused by a single heterozygous missense variant in COL1A1 with incomplete penetrance." (PMID 32033218, 2020).